LINC00885 (long independently transcribed non-coding RNA 885)
Synonyms: PARylator
Gene: Long non-coding RNA gene on chromosome 3 (196,141,940 to 196,193,538, forward strand). Ensembl gene ENSG00000224652.
Diseases named in the same sentence as LINC00885 in open-access papers:
LINC00885 is named in the same sentence as 6 diseases in open-access papers, as found by Europe PMC text mining. Sharing a sentence is not in itself a finding about the gene and the disease. The quoted sentences say what the papers report.
breast cancer (3 papers, 2020 to 2023). A primary or metastatic malignant neoplasm involving the breast. "We conclude that LINC00885 behaves as a positive regulator of cell growth both in normal and DCIS breast cells possibly operating as a ceRNA and representing a novel oncogenic lncRNA associated with early stage breast cancer progression." (PMID 33049922, 2020). "Therefore, LINC00885 acts as a positive regulator of cell growth in normal breast and DCIS cells and may represent a novel oncogenic lncRNA associated with early-stage breast cancer progression." (PMID 37240077, 2023). "Finally, LINC00885 expression may influence early breast cancer progression affecting patient outcome." (PMID 33049922, 2020).
invasive breast carcinoma (1 paper, 2020). A carcinoma that infiltrates the breast parenchyma. "TCGA-BRCA data analyses show an association between high LINC00885 expression and worse overall survival in patients with primary invasive breast carcinomas (p = 0.024), suggesting that the pro-tumorigenic effects of LINC00885 overexpression persist post-invasion." (PMID 33049922, 2020).
cancer (2 papers, 2023). A tumor composed of atypical neoplastic, often pleomorphic cells that invade other tissues. "LINC00885 is encoded by three exons within a locus at chr3q29, and amplification in the LINC00885 gene is observed in 11% of human cancers, including BC." (PMID 37240077, 2023). "Twelve of the LINC00885 target genes were upregulated in cancer tissues, whereas 16 were downregulated." (PMID 36593250, 2023).
tumor (2 papers, 2022 to 2023). "Also, we confirmed that LINC00885 was upregulated in 80 CC tissues versus the paired adjacent non-tumor tissues, and higher expression of LINC00885 predicted lower overall survival of CC patients." (PMID 35012615, 2022). "The overexpression of LINC00885 facilitated tumor growth in vivo." (PMID 35012615, 2022).
LINC00885 also shares sentences with these, for which no sentence is quoted: cervical cancer (2 papers); cervical squamous cell carcinoma (1).